NPM1 (nucleophosmin 1)
Diseases named in the same sentence as NPM1 in open-access papers (continued):
Sharing a sentence is not in itself a finding about the gene and the disease.
tumor (continued). "Although it has been confirmed that overexpression of NPM1 in a variety of gastrointestinal cancers can promote the proliferation and migration of tumor cells, no comprehensive analysis of NPM1 in gastrointestinal cancers has been reported." (PMID 36188614, 2022). "Next, we specifically quantified the tumor-derived fraction of cf-nDNA, termed circulating tumor DNA (ctDNA), using droplet digital PCR (ddPCR) targeting HPV16 E6 and E7 sequences and the NPM1 mutant type A sequence prevalent in the HPV+ HNC and AML patient cohorts, respectively." (PMID 36125881, 2022). "We speculate that the overexpression of NPM1 inhibits the infiltration of B cells and NK cells in LUAD, and ultimately further accelerates tumor progression." (PMID 34335635, 2021). "In tumors with NPM1-ALK fusion, ALK protein may be detected in the nucleus and cytoplasm, while in RANBP2-ALK neoplasms, it shows nuclear membrane staining." (PMID 33237469, 2021). "NPM1, RUNX1, and CEBPA are all genes from common genomic gains observed in a meta-analysis of copy number alterations across a panel of different cancer cell lines and tumor samples." (PMID 29738475, 2018). "Silencing NPM1 abrogated DDX27-activating NF-κB signaling and its tumor-promoting function." (PMID 29535419, 2018). "In addition, we showed that NPM1 was overexpressed in HCC cells and in HCC versus adjacent non-tumor tissues." (PMID 28874807, 2017). "On the other hand, NPM1 failed to predict tumor outcomes in BCLC (B-C) group (P > 0.05) and TNM (III) group (P > 0.05)." (PMID 28874807, 2017). "Experiments with NPM1-knockout cells indicate a tumor-suppressor function for NPM1, both through its role in the maintenance of genomic stability and in the regulation of the alternative reading frame (ARF) tumor-suppressing pathway." (PMID 25779011, 2015). "The protein level of NPM1 was reduced at least 1.5-fold (50% decrease in the expression) in 35% of GC samples, and no tumor presented an increase in expression of 50% compared to their paired non-neoplastic gastric tissue." (PMID 24410879, 2014). "Furthermore, we utilized mRNA display to identify nucleophosmin 1 (NPM/B23), a nucleolar phosphoprotein, as a target of TC11 for inducing apoptosis of tumor cells." (PMID 22761710, 2012). "Notably, NPM1 has been reported to upregulate PD‐L1 transcription, thereby inhibiting T‐cell activity and promoting tumor growth in triple‐negative breast carcinoma." (PMID 41472855, 2025). "This therapeutic potential was translated to amouse model of AML with NPM1 C+ mutation, as intraperitoneal administrationof UCM-13369 resulted in a reduction of tumor infiltration comparedto the untreated group, although no increase in mice survival wasobserved." (PMID 38818079, 2024). "Furthermore, it was observed that the expression of RASGRP3, a protein associated with tumor progression, is upregulated in patients with AML with NPM1 mutation compared to patients with AML without mutant NPM1." (PMID 37296673, 2023). "Among the exclusively detectable Exo-prots in the NB patients, we identified the nucleolar protein NPM1 as being overexpressed in hematologic and solid tumors and ZYX involved in focal adhesion and in the regulation of actin cytoskeleton with a role in cell motility and tumor invasion." (PMID 37947594, 2023). "Therefore, minimal disease detection methods targeting the specific NPM1–ALK fusion RNA do not require initial fresh tumor material for marker analysis." (PMID 33921029, 2021).
tumor (continued). "These cancer patient data support the notion that the NPM1/HIF‐1α interaction also occurs in solid tumors and it is highly involved in the response of cancer cells to the hypoxic tumor microenvironment, which in turn can facilitate tumor growth and resistance to therapy." (PMID 34388291, 2021). "Considering that interferon gamma (IFN-γ) had been reported to induce PD-L1 expression in many tumor cells, we investigated whether it was also the case in stable TNBC cell lines with NPM1 silenced by lentiviral short-hairpin RNA (shRNA) and downregulated PD-L1." (PMID 32245950, 2020). "While we did not break down the analysis by tumor type, the majority (86%) of the analyzed data related to preclinical studies using transformed cell lines, expressing either NPM1-ALK-based constructs or EML4-ALK-based constructs, thus effectively normalizing the analysis." (PMID 30675517, 2019). "In this study, we found NPM1 to be overexpressed in tumor cells compared to adjacent normal tissue." (PMID 26993766, 2016). "Nucleolar NPM1 was detected in cells from all tumor samples regardless of grade." (PMID 26559910, 2015). "Although genetic analysis implicates NPM1 in tumorigenesis, it is still not clear whether NPM1 may operate either as an oncogene or a tumor-suppressor gene, perhaps with dual functions." (PMID 25779011, 2015). "Recently it was shown that STAT5a could be epigenetically silenced by the tyrosine kinase NPM1-ALK resulting in the lack of reciprocal inhibition of this oncogenic kinase by STAT5a providing some evidence of a possible tumor suppression function for STAT5a." (PMID 21655368, 2008). "A related useful aspect of mutant NPM1 immunostaining is that it can provide helpful information when the cellularity of BM aspirate and PB specimens used for bulk studies (i.e., RT-PCR, NGS and FC) may be variable (e.g., due to a “packed-marrow”) and may underestimate tumor cell number (Sample 64)." (PMID 34527579, 2021). "Therefore, NPM1 is not your “typical” tumor suppressor gene." (PMID 21152184, 2011). "The HT1080 cells knocked down for NPM1 and carrying Dox-inducible p27 were transplanted into the back of BALB/c-nu nude mice and the tumor growth was monitored with or without Dox feeding." (PMID 33050036, 2020). "Finally, these genes were overlapped with the upregulated DEGs from the two GSE9782 datasets, resulting in 7 tumor stemness-related genes, including NONO, CBX3, SLC25A3, PTPRG, NPM1, HINT1, HNRNPA1." (PMID 41050668, 2025). "Moreover, patients experiencing tumor recurrence, after at least one year from diagnosis, had fifty-four genes that were positively correlated with APE1/NPM1, while sixty-one had negative correlation." (PMID 31307523, 2019). "Thus, here we supposed that in ccRCC, the attenuation of ALDH9A1 fails to retain NPM1 in the cytoplasm and promote its accumulation in the nuclear, leading to inhibition of IQGAP2 and subsequent activation of AKT-mTOR signaling to support tumor progression and lipid accumulation." (PMID 39039052, 2024).
cancer (220 papers, 2003 to 2026). A tumor composed of atypical neoplastic, often pleomorphic cells that invade other tissues. "In solid tumors, NPM1 is rarely mutated but it is frequently overexpressed in multiple cancers, including CRC, hepatic and lung." (PMID 41413654, 2026). "The outer granular component (GC) of the nucleolus in human cells is densely packed with the negatively charged protein nucleophosmin (NPM1) that scaffolds the phase separation of the GC and has long been implicated in cancer." (PMID 39545954, 2024). "Using KEGG pathway enrichment analysis, we found that co-mutations in CN-AML with NPM1 mutations were related to cancer and metabolism." (PMID 39767827, 2024). "Second, we conducted an in-depth investigation on the underlying mechanism of NPM1 in cancer cell progression and its potential relationship with c-Myc." (PMID 37875480, 2023). "NPM1 is mutated in cancers such as AML, accounting for about 30% of the cases, which makes it an attractive target for future cancer therapies." (PMID 35740532, 2022). "The role of NPM1 in human cancer has received a new spotlight with the discovery of mutations of exon 12 of NPM1 in approximately 30% of adult de novo AML, and in 50–60% in those with a normal karyotype." (PMID 35054502, 2022). "Accordingly, we believe that the cancer-promoting effect of NPM1 gene is associated with cuproptosis related genes expression." (PMID 36188614, 2022). "A previous study in cancer cells has reported that Puf-A is a nucleolar protein and is associated with the nucleolar protein, nucleophosmin (NPM1)." (PMID 35563782, 2022). "Many nucleolar factors, such as nucleophosmin (NPM1, also known as B23) and ribosomal proteins, participate in cancer growth in which robust ribosome biosynthesis is a hallmark." (PMID 34999733, 2022). "TCR CAR T-cells have successfully targeted intracellular synovial sarcoma X breakpoint 2 (SSX2) in the context of HLA*0201 as well as mutated nucleophosmin (NPM1) in the context of HLA-A2 in AML cancer cell lines." (PMID 35158765, 2022). "Accordingly, NPM1 is overexpressed in highly proliferative cells and has been proven to be associated with several types of cancer." (PMID 34885010, 2021). "Depletion of NPM1 or disruption of its association with HIF‐1α selectively curtails the ability of cancer cells to survive under low oxygen." (PMID 34388291, 2021). "In concert, silencing of NPM1 expression or disruption of its association with HIF‐1α inhibits metabolic adaptation of cancer cells and triggers apoptotic death upon hypoxia." (PMID 34388291, 2021). "As already mentioned, NPM1 expression is increased in various cancer types and it has been associated with progression to more advanced stages of disease." (PMID 34388291, 2021). "Recently, an important role for NPM1 in miRNA biology, associated with cancer development, was outlined." (PMID 31913336, 2020). "NPM1 overexpression, chromosomal translocation or mutations of the NPM1 gene, are associated with many cancer types, both solid and hematological malignancies." (PMID 32664415, 2020). "The association of NPM1/APE1 with cancer gene signatures highlighted alterations concerning cell-cycle dependent proteins." (PMID 31307523, 2019). "For deeper insight into the anticancer mechanism of NPM1 inhibition in AT/RTs, we entered the identified 88 cancer-associated genes that were deregulated in AT/RT samples into GeneMANIA software (version 3.1.2.8) for network analysis." (PMID 31462227, 2019). "In order to generalize our findings and to investigate the APE1 and NPM1 overall influence and association with specific gene-signatures on tumorigenesis, we then followed a more global approach using the available cancer datasets from TCGA." (PMID 31307523, 2019). "To evaluate the translation of the splice variants on the protein level, we performed Western blot analysis in selected cancer cell lines which revealed differential expression of NPM1 splice variants in leukemic myeloid cells." (PMID 29221119, 2017).
cancer (continued). "The aim of this review is to look at the less well-described role of NPM1 in the DNA repair pathways as well as the role of NPM1 in the regulation of apoptosis and its mutation in cancers." (PMID 27553022, 2016). "NPM1 was first associated with cancer where approximately one-third of anaplastic large-cell non-Hodgkin’s lymphomas were found to express a fusion between NPM1 and the catalytic domain of anaplastic lymphoma receptor tyrosine kinase (ALK)." (PMID 27553022, 2016). "NPM1 function is a critical requirement for normal cellular biology as is underlined in cancer where NPM1 is commonly overexpressed, mutated, rearranged and sporadically deleted." (PMID 27553022, 2016). "Pearson correlation coefficient (r) between every gene in these four datasets and one cancer-associated gene (e.g., NPM1) was calculated independently in each dataset." (PMID 25961029, 2015). "Even though our study showed the possibility of HDAC inhibitor for patients in the high-risk group, inhibition of NPM1 based on not only the direct effect on NPM1 itself but also indirect effects including sensitizing cancer cells would be the promising treatment strategy in the future." (PMID 38467827, 2024). "HIF-1α- and NPM1-regulated genes significantly overlapped and disruption of the HIF-1/NPM1 association with cell penetrating peptides derived from the ETD sequence of HIF-1α inhibited cancer cell proliferation and survival under hypoxia by triggering apoptosis." (PMID 36899934, 2023). "ENO1, NDRG1 and NPM1 are reportedly associated with cancer as further discussed." (PMID 38097352, 2023). "The cytoplasmic mis-localization of the shortened NPM1 variant might influence the leukemic burden, thus providing the rationale for application of the nuclear export inhibitors in cancer with either mutated NPM1 or high expression level of NPM1." (PMID 36282861, 2022). "Moreover, we found that NPM1 was strongly associated with patient prognosis in several cancers and acted as an unfavorable prognostic factor." (PMID 34899858, 2021). "Therefore, interfering with the ability of NPM1 N-terminal domain to self-associate has been considered an amenable option to inhibit NPM1 specific roles within cancer cells." (PMID 32664415, 2020). "Another leukemogenic protein which might be related to chromatin-bound CRM1 is nucleophosmin 1 (NPM1), a multifunctional nucleolar protein that is frequently overexpressed or mutated in human cancers." (PMID 31755865, 2019). "Expression of the NPM1 gene, encoding nucleophosmin, is upregulated in cancers." (PMID 30126426, 2018). "Some of the interest in NPM1 stems from the fact that genetic alterations of the NPM1 gene are associated with haematological cancer, while overexpression of NPM1 has been found in a variety of other cancers." (PMID 30357352, 2018). "These and other observations led to the suggestion that the NPM1 region/s implicated in protein partners recognition may be considered a target for cancer treatment." (PMID 28920929, 2017). "Of course, because overexpression or mutation of NPM1 is frequently detected in human cancer tissues, we wonder whether NPM1 expression is increased in A549-CUG2 and BEAS-CUG2 cells." (PMID 27974707, 2017). "Indeed, as evidence of NPM1 function in DNA repair pathways increases, it explains at least in part the genetic instability associated with cancers such as AML." (PMID 27553022, 2016). "Ac-NPM1 is preferentially found in the nucleoplasm in association with RNA polymerase II and the increase in Ac-NPM1 seen in cancer could be of mechanistic importance." (PMID 21152184, 2011). "In humans, nucleophosmin (NPM1) is implicated in the genesis of different cancers." (PMID 20877721, 2010). "Moreover, proliferative organs like the intestine and skin retained Npm1 deletion without gross phenotypes, suggesting that although associated with cancer cell proliferation, NPM1 is dispensable for normal homeostatic proliferation, implying probable tolerance for drug targeting." (PMID 41413654, 2026).
cancer (continued). "Therefore, the qualitative suppression of p27 by NPM1 could occur in various types of cancer in which ARF deficiency leads to high NPM1 expression." (PMID 33050036, 2020). "Treatment strategies that sensitize gemcitabine via inhibition of NPM1 oligomerization activity by NSC348884 can be further employed as a rational cancer therapy for CSN6‐high PDAC, especially in gemcitabine‐resistant patients." (PMID 41114465, 2026). "Given the protumoral functions of NPM1 across various cancer types, it holds significant potential as a therapeutic target." (PMID 40705480, 2025). "It has been shown that NPM1 interacts with the oncogenic transcription factor FOXM1 in cancer cells." (PMID 38928092, 2024). "In the proteomic cluster featured with the high cell proliferation rate, APEX1 and NPM1 are found to promote cell proliferation and drive the progression of cancer cells." (PMID 38360860, 2024). "Several processes, including HIV1 infection and drug resistance in cancer cells, depend on the induction and stabilization of NPM1 acetylation." (PMID 39120297, 2024). "Our aim was to utilize high-depth targeted regional sequencing (TRS) technology to detect more myeloid-cancer-related mutations, combined with clinical data, to estimate the prognosis of adults with CN-AML harboring NPM1 mutations." (PMID 39767827, 2024). "Various human cancer cell lines were used to validate the role of NPM1 in regulating the transcription of PD-L1." (PMID 38243170, 2024). "We demonstrated that NPM1 enhanced the transcription of PD-L1 in various types of cancer, and the acetylation of NPM1 played a vital role in this process." (PMID 38243170, 2024). "Using pharmacological inhibitors of NPM1 to induce apoptosis in cancer cells, reports have monitored the anti-apoptotic properties of NPM1." (PMID 39120297, 2024). "As bromodomain containing 4 (BRD4) is a well-known and effective BET protein and is well acknowledged in cancers for its oncogenic roles, we tested the relationship of NPM1 and BRD4." (PMID 37875480, 2023). "Consistently, we observed that NPM1 expression in PCa tissues was higher than that in prostate non-cancer tissues." (PMID 37875480, 2023). "This includes functionally relevant proteins associated with LN metastasis in cancer such as KRT7, KRT19, SRI, NPM1, Annexin A2 (ANXA2), Annexin A5 (ANXA5)." (PMID 37142981, 2023). "These genes have varying supporting functions expected from a cancer cell population, including, for example, supporting cell proliferation (NPM1) and telomere maintenance (NHP2)." (PMID 36598637, 2023). "Nucleophosmin 1 (NPM1), also known as nucleolar phosphoprotein B23 or numatrin, has been implicated in the development of cancer." (PMID 36674758, 2023). "MTS assays showed that single knockdown of NPM1 drastically reduced the growth rate of LNCaP and 22Rv1 cells, while single knockdown of c-Myc had a more prominent impact on cancer cell proliferation." (PMID 37875480, 2023). "In contrast to AML, studies on the role and function of NPM1 in solid tumours are rare; however, NPM1 is frequently overexpressed in various cancer cells." (PMID 37251542, 2023). "The disruption of NPM1 oligomerization by NSC348884 has been shown to lead to apoptosis in cancer cells." (PMID 37870957, 2023).